VSTM2A (V-set and transmembrane domain containing 2A)
Description:
Plays a role in the regulation of the early stage of white and brown preadipocyte cell differentiation. Promotes adipogenic commitment of preadipocytes by increasing gene expression of the transcription factor PPARG in a BMP4-dependent signaling pathway.
Synonyms: VSTM2; MGC33530
Tractability: Antibody: UniProt places it where antibodies can reach, with medium confidence; UniProt predicts a signal peptide or a membrane-spanning region; its Gene Ontology location is reachable by antibodies, with medium confidence.
Gene: Protein-coding gene on chromosome 7 (54,542,325 to 54,571,080, forward strand). Ensembl gene ENSG00000170419.
Subcellular location: Secreted
Gene Ontology:
Molecular function: protein binding; identical protein binding
Biological process: positive regulation of brown fat cell differentiation; positive regulation of gene expression; positive regulation of lipid storage; positive regulation of white fat cell proliferation; cellular response to BMP stimulus
Cellular component: nucleus; extracellular region; membrane
Genetic constraint (gnomAD): Loss-of-function variants: 13 observed, 27.67 expected, observed/expected ratio (o/e) 0.47, 90% interval 0.31 to 0.75. The upper end of that interval is the gene's LOEUF score, 0.75, which puts it in group 3 of 6, group 1 being the genes least tolerant of losing a copy. Missense variants: 280 observed, 315.33 expected, observed/expected ratio (o/e) 0.89, 90% interval 0.81 to 0.98. Synonymous variants: 142 observed, 130.03 expected, observed/expected ratio (o/e) 1.09, 90% interval 0.95 to 1.25.
Homologues: Orthologues: chimpanzee VSTM2A (99% identical), macaque VSTM2A (96% identical), rat Vstm2a (80% identical), mouse Vstm2a (80% identical), pig VSTM2A (80% identical), guinea pig VSTM2A (71% identical), dog VSTM2A (60% identical), zebrafish vstm2a (50% identical). Paralogues in human: IGSF3 (22% identical), CD101 (21% identical), PTGFRN (20% identical), IGSF8 (20% identical), VSTM4 (8% identical).
Diseases named in the same sentence as VSTM2A in open-access papers:
VSTM2A is named in the same sentence as 14 diseases in open-access papers, as found by Europe PMC text mining. Sharing a sentence is not in itself a finding about the gene and the disease. The quoted sentences say what the papers report.
colon cancer (4 papers, 2019 to 2022). "The ectopic expression of VSTM2A inhibits the growth of colon cancer cell lines and organoids, induces CRC cell apoptosis, inhibits cell migration and invasion, and inhibits the growth of xenograft tumors in nude mice." (PMID 35836256, 2022). "Ectopic expression of VSTM2A inhibited colon cancer cell lines and organoid growth, induced CRC cells apoptosis, inhibited cell migration and invasion, and suppressed growth of xenograft tumors in nude mice." (PMID 31588233, 2019). "IHC staining showed that human-derived normal colon organoid showed a high expression of VSTM2A on the cell membrane compared with patient-derived colon cancer organoid." (PMID 31588233, 2019). "The secreted VSTM2A significantly inhibits the Wnt signaling pathway in colon cancer cells." (PMID 35836256, 2022). "Consistently, VSTM2A significantly inhibited the expression of Wnt target genes cyclin D1 and c-myc, and β-catenin activation, but did not change β-catenin mRNA expression in 293T and RKO cells, suggesting secreted protein VSTM2A negatively regulated Wnt signaling pathway in colon cancer." (PMID 31588233, 2019). "Secreted VSTM2A significantly suppressed Wnt signaling pathway in colon cancer cells." (PMID 31588233, 2019).
colorectal cancer (4 papers, 2019 to 2024). A primary or metastatic malignant neoplasm that affects the colon or rectum. "EGFR-VSTM2A fusion was detected in one case of colorectal cancer and another case occurring upstream of the VSTM2A gene in lung cancer." (PMID 36369474, 2022). "V-set and transmembrane domain containing 2A (VSTM2A) is a secretory protein that is lowly expressed in colorectal cancer tissue." (PMID 34589484, 2021). "In this study, we identified that V-set and transmembrane domain containing 2A (VSTM2A) was a top-downregulated secreted protein that negatively regulated Wnt singling pathways in colorectal cancer (CRC)." (PMID 31588233, 2019). "VSTM2A interacts with the extracellular domain of LRP6 and inhibits LRP6 phosphorylation, thereby inducing its lysosomal degradation, and suppressing colorectal cancer progression." (PMID 34589484, 2021).
Alzheimer disease (1 paper, 2024). A progressive, neurodegenerative disease characterized by loss of function and death of nerve cells in several areas of the brain leading to loss of cognitive function such as memory and language. "Given the PD-L1/PD-1, mTOR, and Wnt pathways play essential roles in the proper differentiation of cortical layers, cognitive development, brain injury, and Alzheimer’s disease, it is plausible that VSTM2A is indispensable in the maintenance of human central nervous system." (PMID 39289872, 2024).
colitis (1 paper, 2024). Inflammation of the colon. "Therefore, we challenged mice with the carcinogen azoxymethane (AOM) combined with inflammation-inducer dextran sodium sulfate (DSS) to study the function of VSTM2A in the colitis-associated CRC mice model." (PMID 39289872, 2024).
gastric cancer (1 paper, 2019). A primary or metastatic malignant neoplasm involving the stomach. "In addition, we observed that both overexpression of VSTM2A and recombinant VSTM2A protein significantly suppressed gastric cancer cell growth." (PMID 31588233, 2019).
glioblastoma (1 paper, 2018). The most malignant astrocytic tumor (WHO grade IV). "VSTM2A, LANCL2, SEC61G and VOPP1 were also amplified and are reported in the literature as fusion genes with EGFR in some glioblastoma patients." (PMID 29844869, 2018).
glioma (1 paper, 2010). A benign or malignant brain and spinal cord tumor that arises from glial cells (astrocytes, oligodendrocytes, ependymal cells). "The expression of 5 genes (VSTM2A, SEPT14, MRPS17, PSPH and CCT6A) was undetectable in all these gliomas, regardless of their amplification status." (PMID 21170331, 2010).
schizophrenia (1 paper, 2024). A major psychotic disorder characterized by abnormalities in the perception or expression of reality. "Within the CGE, genes with high expression specificity for two calretinin (CALB2)-positive sub-populations of developing GABAergic neurons were also enriched for schizophrenia genetic liability (CGE-N-1, marker: NRIP3, and CGE-N-2, markers: BEX2, ARL6IP5, VSTM2A)." (PMID 38869145, 2024).
tumor (6 papers, 2010 to 2024). "Utilizing the VSTM2A protein as an immunotherapeutic agent would potentially show higher anti-tumor efficiency." (PMID 39289872, 2024). "More importantly, our studies reveal the multi-function of VSTM2A in tumor-intrinsic Wnt/β-catenin pathway inhibition and tumor-extrinsic immune activation via antagonizing PD-L1 signaling." (PMID 39289872, 2024). "At the time of harvest (day 80), all Vstm2a+/− mice developed visible abnormalities in colon tissue, whereas the tumor incidence was 61% in wild-type mice." (PMID 39289872, 2024). "Total tumor loads in Vstm2a+/− mice were significantly higher than those of wild-type mice (p < 0.0001 and p < 0.01, respectively)." (PMID 39289872, 2024). "In summary, we identified the tumor-extrinsic role of VSTM2A in regulating T cell activation through antagonizing PD-1/PD-L1-mediated suppressive signaling." (PMID 39289872, 2024). "The overall survival analysis had finalized GLP2R and VSTM2A genes that were significantly downregulated in tumor samples and had a strong correlation with immunocyte infiltration." (PMID 37076536, 2023). "It was found that VSTM2A gene expression was markedly reduced in the CRC dataset tumor samples in comparison to normal samples." (PMID 34253750, 2021). "Strong expression of VSTM2A was found in normal epithelium compared with paired tumor regions using IHC staining." (PMID 31588233, 2019). "Consistently, VSTM2A mRNA was significantly decreased in tumor tissues compared with normal epithelial cells by real-time PCR (P < 0.01)." (PMID 31588233, 2019). "In summary, we revealed that secreted protein VSTM2A is a critical tumor suppressor in colorectal carcinogenesis and a novel antagonist of Wnt signaling receptor LRP6." (PMID 31588233, 2019). "Tumor samples were stratified into high and low expression groups based on VSTM2A staining assessed by two independent pathologists." (PMID 31588233, 2019). "VSTM2A promoter methylation was significantly higher in tumor tissues compared with the normal colon tissues in our cohort (N = 8, P < 0.001) and in TCGA-COAD DNA Methylation Array Methylation450k cohort (N = 395, P < 0.0001)." (PMID 31588233, 2019). "Collectively, our results suggest that VSTM2A plays a pivotal tumor suppressive role in CRC cells through inhibiting cell proliferation and promoting apoptosis." (PMID 31588233, 2019). "Among these genes, the SEC61G gene was co-amplified with EGFR in 5 tumours and the VSTM2A gene in 4 of them." (PMID 21170331, 2010). "Patients with inferior VSTM2A mRNA expressions showed a significantly lower ImmuneScore in both early and late stages in the two datasets, indicating a lack of VSTM2A expression associated with cold tumor environments." (PMID 39289872, 2024). "In addition to VSTM2A’s tumor-intrinsic role in regulating the Wnt pathway, we further explore its tumor-extrinsic role in regulating the tumor microenvironment." (PMID 39289872, 2024). "Therefore, in this study, we continued to elucidate the tumor-extrinsic function of VSTM2A in colorectal carcinogenesis." (PMID 39289872, 2024). "Pathological examination of the tumors developed in Vstm2a+/− mice further confirmed high-grade dysplasia and adenocarcinoma, whereas normal colon epithelium or limited low-grade dysplasia were observed in the control group, echoing our previous report of VSTM2A as a tumor suppressor in CRC." (PMID 39289872, 2024). "Future studies are needed to test whether the VSTM2A protein could also enhance the potency of autologous tumor-reactive T cell therapy and NK cell-based cancer immunotherapy." (PMID 39289872, 2024). "The gene VSTM2A encodes V-set and transmembrane domain containing 2A which was previously reported to be a tumor suppressor although not in brain tissues and some studies found that tumor suppressor responses can be associated with AD." (PMID 33282526, 2020).
tumor (continued). "In this study, we provide a series of experimental evidences that VSTM2A is a critical tumor suppressor in CRC and a novel antagonist of Wnt signaling by direct binding to Wnt co-receptor LRP6, suppressing LRP6 activation and inducing its endocytosis and degradation." (PMID 31588233, 2019). "In light of our in vitro findings, we examined the in vivo tumor suppressive ability of VSTM2A." (PMID 31588233, 2019). "Using a series of in vitro and in vivo functional experiments, VSTM2A possesses a tumor-suppressive function through inhibiting CRC cell proliferation, migration/invasion, and organoid growth, induced apoptosis in vitro and suppressed xenograft tumor growth in nude mice." (PMID 31588233, 2019). "We validated the tumor suppressive role of VSTM2A in organoid models." (PMID 31588233, 2019). "Our previous study reported that VSTM2A was an antagonist of Wnt ligands by competitively binding with membrane protein LRP6 and induced LRP6 endocytosis-dependent degradation, which in turn suppressed tumor-intrinsic Wnt/β-catenin signaling activation." (PMID 39289872, 2024). "Our study demonstrated that VSTM2A positively correlated with CD8+ T cell infiltration and antagonized the PD-L1/PD-1 inhibitory signal; therefore, administration of VSTM2A would inhibit CRC tumor cell growth directly while favoring lymphocyte tumor infiltration and activation." (PMID 39289872, 2024).
cancer (4 papers, 2019 to 2024). A tumor composed of atypical neoplastic, often pleomorphic cells that invade other tissues. "Loss of VSTM2A may cause Wnt signaling hyper-activation in colon and finally lead to cancer development." (PMID 31588233, 2019). "PD-L1 can elicit diverse functions beyond immunosuppressive signaling pathways in cancer, implying that the VSTM2A/PD-L1 interaction could have broad functional significance in other conditions." (PMID 39289872, 2024).
VSTM2A also shares sentences with these, for which no sentence is quoted: COVID-19 (3 papers); lung carcinoma (2); adenocarcinoma (1); liver cancer (1).